PUM1 (pumilio RNA binding family member 1)
Diseases named in the same sentence as PUM1 in open-access papers (continued):
Sharing a sentence is not in itself a finding about the gene and the disease.
non-small cell lung carcinoma (6 papers, 2019 to 2025). A group of at least three distinct histological types of lung cancer, including non-small cell squamous cell carcinoma, adenocarcinoma, and large cell carcinoma. "MicroRNA-411-5p functioned as a tumor suppressor by blocking the translation of the PUM1 mRNA in non-small cell lung cancer, suggesting that PUM1 also acts as an oncogene." (PMID 41155797, 2025). "IFFO1 methylation participates in non-small-cell lung cancer, and PUM1 is an RNA-binding protein gene that participates in multiple biological processes, such as translational regulation and cell development." (PMID 32528944, 2020). "PUM1 can inhibit the proliferation of non-small-cell lung cancer cells via targeted by MiR-411-5p and can mediate the interaction between p27 and MiR-221, which leads to the deterioration of non-small-cell lung cancer." (PMID 32528944, 2020). "Therefore, the hypermethylation of PUM1 is an important epigenetic characteristic for non-small-cell lung cancer diagnosis." (PMID 32528944, 2020). "In non-small cell lung cancer, tumor suppressor miR-340 directly binds to the 3′UTR of Pum1 and Pum2 mRNA to inhibit their expression, thus reducing PUM1 and PUM2 that are required for the miR-221/222 interaction with the p27 3′UTR64." (PMID 35338151, 2022). "miR-340 was shown to induce the accumulation of p27 and subsequent cell cycle arrest by targeting three negative regulators of p27: PUM1, PUM2, and SKP2, indicating that miR-340 could repress non-small cell lung cancer (NSCLC) cell proliferation." (PMID 33390846, 2021).
developmental delay (4 papers, 2019 to 2024). "Although PUMs have many targets and are expressed in many cell-types, PUM1 haploinsufficiency causes epilepsy and developmental delay." (PMID 38898501, 2024). "On the flipside, a recent study in humans showed that halving the dose of PUM1 leads to developmental delay and seizures, and reducing the amount of PUM1, PUM2, or both results in smaller body size." (PMID 30848246, 2019). "Different mutations in the RNA‐binding protein Pumilio1 (PUM1) cause divergent phenotypes whose severity tracks with dosage: a mutation that reduces PUM1 levels by 25% causes late‐onset ataxia, whereas haploinsufficiency causes developmental delay and seizures." (PMID 37070548, 2023).
gastric cancer (4 papers, 2015 to 2025). A primary or metastatic malignant neoplasm involving the stomach. "In clinical samples of gastric cancer, high PUM1 expression was also associated with recurrence, metastasis, and poor survival." (PMID 41155797, 2025). "Moreover, PUM1 causes metabolic reprogramming in gastric cancer by post-transcriptionally regulating the DEP domain-containing mTOR-interacting protein (DEPTOR)." (PMID 41155797, 2025). "Pumilio 1 (PUM1), an RNA binding protein, induces metabolic reprogramming through post‐transcriptional regulation of DEP domain‐containing mammalian TOR (mTOR)‐interacting protein (DEPTOR) in gastric cancer (GC)." (PMID 37469018, 2023).
viral infection (4 papers, 2014 to 2025). "Our study expands the understanding of the immunomodulatory roles of PUM1 in the context of viral infection, specifically during SARS-CoV-2 replication." (PMID 40666984, 2025). "There is an intriguing discrepancy regarding the role of PUM1 in viral infections: it appears antiviral against NDV, proviral for HSV-1, and largely neutral for SARS-CoV-2." (PMID 40666984, 2025). "A limitation of this study is that all experiments were conducted in cell culture, and it remains unclear whether PUM1 plays a significant role in viral infection within an organism." (PMID 40666984, 2025). "Viral infection induces the formation of avSGs, including conventional SG markers, RIG-I, MDA5, LGP2, PKR, OAS, RNase L, DHX36, TRIM25, PUM1 and PUM2, some of which are critical in sensing non-self viral RNA and triggering antiviral signaling." (PMID 25340845, 2014).
osteoarthritis (3 papers, 2023 to 2025). A noninflammatory degenerative joint disease occurring chiefly in older persons, characterized by degeneration of the articular cartilage, hypertrophy of bone at the margins and changes in the synovial membrane. "Injections of a lentiviral vector carrying PUM-1 protected the knee cartilage integrity in a mouse model of medial meniscus damage-induced osteoarthritis." (PMID 39062974, 2024). "Downregulating TLR4 through PUM1 can help reduce cellular aging and osteoarthritis, indicating its potential therapeutic implications for age-related diseases." (PMID 37240754, 2023). "Additionally, PUM1 was found to be downregulated in damaged cartilage tissues from patients with osteoarthritis (OA)." (PMID 39062974, 2024).
Cerebral ischemia (2 papers, 2022 to 2025). Restriction of arterial blood supply to the brain associated with insufficient oxygenation to support the metabolic requirements of the tissue. "Finally, circRNA Pum1 with a previous role mitigating cerebral ischemia was found in upregulated early-stage ceNET, which may reflect a compensatory response." (PMID 40332030, 2025).
epilepsy (2 papers, 2022 to 2024). A brain disorder characterized by episodes of abnormally increased neuronal discharge resulting in transient episodes of sensory or motor neurological dysfunction, or psychic dysfunction. "Upon thoroughly reviewing the existing literature, nine cases of PUM1 mutation-related epilepsy were identified, and their clinical features were summarized." (PMID 35386260, 2022). "Added to this, vascular-localized granular PUM1 was observed in the hippocampus of patients with psychiatric disorders and epilepsy." (PMID 38898501, 2024). "Based on our accumulated data, we sought to examine whether granular PUM1 can be impacted in the CLDN-5 translational efficacy in patients with psychiatric disorders and epilepsy." (PMID 38898501, 2024).
melanoma (2 papers, 2020 to 2021). A malignant, usually aggressive tumor composed of atypical, neoplastic melanocytes. "However, in both melanomas secondary copy number alterations of the CYSLTR2 locus (chromosome 13q) were observed as well: PUM-1 showed loss of the wild-type allele, while in PUM-2 the mutant allele was gained." (PMID 33588787, 2021).
schizophrenia (2 papers, 2024). A major psychotic disorder characterized by abnormalities in the perception or expression of reality. "CLDN-5, PUM1 and PUM2 mRNA levels in the post-mortem hippocampal sections of patients with bipolar (BP), schizophrenia (SCZ) and major depressive disorders (MDD) were measured as BBB integrity in the hippocampus is especially vulnerable to oxidative damage and other stress related stimuli." (PMID 38898501, 2024).
adenoma (1 paper, 2022). A neoplasm arising from the epithelium. "H&E staining further revealed a significant decrease of adenomas when Pum1 and Pum2 were knocked down." (PMID 35338151, 2022). "In addition, there was a profound decrease in adenomas that display a high grade of dysplasia in Pum1/2CKO mice." (PMID 35338151, 2022).
bile duct cancer (1 paper, 2021). "Conversely, however, a study that used dPCR and bioinformatics methods to identify genic fusion of PUM1 and TRAF3, which was associated with poor survival in bile duct cancer patients, suggested that PUM1 is involved in the initial tumorigenic process." (PMID 33522650, 2021). "Here, we selected the PUM1 gene because it has been shown in basic and clinical research to be an excellent housekeeping gene, and it was associated with poor prognosis for bile duct cancer through the formation of a genic fusion." (PMID 33522650, 2021).
breast tumor (1 paper, 2010). "The first dataset includes relative expression levels of 6 reference genes (ACTB, GAPDH, MRPL19, PSMC4, PUM1, and SF3A1) quantified in 80 breast tumor samples." (PMID 20470420, 2010).
colitis (1 paper, 2022). Inflammation of the colon. "Intestine-specific knockout of Pum1 and Pum2 in mice significantly inhibits the progression of colitis-associated cancer in the AOM/DSS model." (PMID 35338151, 2022).
colorectal tumor (1 paper, 2022). "Instead, we found that conditional knockout of Pum1 and Pum2 effectively blocked the occurrence and development of colorectal tumors." (PMID 35338151, 2022). "Furthermore, we show that intravenous injection of nanoparticles encapsulated with anti-Pum1 and Pum2 siRNAs significantly inhibits the growth of human colorectal tumors in mice." (PMID 35338151, 2022). "Perhaps most importantly, when we treated colon orthotopic implant tumors by tail vein injection of nanoparticles encapsulated with anti-Pum1/2 siRNAs, these siRNAs prevented the further growth of colorectal tumors without obvious effects on other organs." (PMID 35338151, 2022).
cryptococcosis (1 paper, 2014). An acute or chronic, localized or disseminated infection by Cryptococcus neoformans. "Here we examined the wildtype XL280, the pum1Δ mutant, and the PGPD1-PUM1 strain in the inhalation infection model of murine cryptococcosis." (PMID 24901238, 2014).
Hyperglycemia (1 paper, 2017). An increased concentration of glucose in the blood. "Over increasing durations of hyperglycemia exposure, SP1 mRNA levels were evaluated in HRECs and ARPE-19 cells after normalization relative to the mRNA levels of Pumilio homolog 1 (PUM1) and peptidylprolyl isomerase A (PPIA), respectively." (PMID 28706953, 2017).
Infertility (1 paper, 2020). "Notably, we found that a number of mRNAs that are enriched in TCam-2 cells compared to somatic gonadal tissue or cause infertility when mutated are under the control of PUM1 or PUM2 RNA regulons, which is in line with their divergent functions." (PMID 32316190, 2020). "Therefore, establishing the mechanisms underlying functional divergence of PUM1 and PUM2, including identification of their protein cofactors, may help in understanding their particular roles in human germ cells as well as human infertility, a problem affecting 15% of couples world-wide." (PMID 32316190, 2020).
metastasis (1 paper, 2023). The spread or migration of cancer cells from one part of the body (where they first appeared) to another. "Moreover, increased expression of PUM1 was also associated with tumor size, pathologic TNM (pTNM) stage, lymph node metastasis, lymphatic vessel invasion, and depth of invasion." (PMID 37469018, 2023).
osteoporosis (1 paper, 2022). A condition of reduced bone mass, with decreased cortical thickness and a decrease in the number and size of the trabeculae of cancellous bone (but normal chemical composition), resulting in increased fracture incidence. "With respect to the pathological bone formation, the PUM1 gene was differentially expressed in osteoporosis-related cells." (PMID 35371093, 2022).
Parkinson disease (1 paper, 2008). A progressive degenerative disorder of the central nervous system characterized by loss of dopamine producing neurons in the substantia nigra and the presence of Lewy bodies in the substantia nigra and locus coeruleus. "For instance, angiogenesis-related proteins were mainly enriched among PUM1 targets whereas the transcripts coding for proteins linked to Parkinson's disease were solely enriched among PUM2 targets." (PMID 18776931, 2008).
prostate carcinoma (1 paper, 2021). A carcinoma that arises from epithelial cells of the prostate gland. "Although the transcription factors of stemness genes have similar expressions, they have different contributions between normal and prostate cancer tissues; and particular transcription factors enhance the stemness of prostate cancer, such as PUM1, CLOCK, SP1, TCF12, and so on." (PMID 33985534, 2021).
psoriasis (1 paper, 2022). An autoimmune condition characterized by red, well-delineated plaques with silvery scales that are usually on the extensor surfaces and scalp. "Besides, our study revealed the mRNA surveillance pathway and two diagnostic gene biomarkers (PUM1 and ZFP91) for the osteoarticular involvement in psoriasis and AS." (PMID 35371093, 2022). "Finally, we identified PUM1 and ZFP91 as the optimal diagnostic biomarkers for osteoarticular involvement in psoriasis and AS." (PMID 35371093, 2022).
rectal cancer (1 paper, 2020). A primary or metastatic malignant neoplasm that affects the rectum. "Using GAPDH and PUM1 as the reference gene for the validation phase, rectal cancer patients with stage III/IV showed a 4.79-fold change (P=0.006) in ALDH1 expression, and an 11.76-fold change in Twist expression (P=0.003) with respect to stage II rectal tumor when normalized with GAPDH and PUM1." (PMID 33457124, 2020). "The genes evaluated for rectal cancer and normal rectal samples in our study included GAPDH, RPNI, PUM1, B2M, and PMM1, which are involved in the process of transcription/translation; other genes are involved in nucleotide metabolism, are a part of the cytoskeleton, etc.." (PMID 33457124, 2020).
rectal tumors (1 paper, 2020). "GAPDH and PUM1 can be used as an optimal set of housekeeping genes for gene expression-related experiments in rectal tumors." (PMID 33457124, 2020). "GAPDH, RPN1, and PUM1 could be used as a suitable reference gene for gene expression-based qPCR experiments in rectal tumors." (PMID 33457124, 2020). "In the validation phase, 10 new rectal tumors were evaluated taking the geometric mean of GAPDH and PUM1 as the reference gene." (PMID 33457124, 2020). "The GAPDH and PUM1 combination was used successfully for normalization in the experiment related to the CSCs and EMT markers ALDH1, E cadherin, vimentin, and Twist expression in rectal tumors." (PMID 33457124, 2020). "However, in rectal tumors, we found GAPDH, PUM1, and RPN1 with the most stably expressed reference genes." (PMID 33457124, 2020). "Five promising reference genes GAPDH, Pumilio RNA binding family member 1 (PUM1), beta-2-microglobulin (B2M), ribophorin I (RPN1), and phosphomannomutase 1 (PMM1) were selected from different publications to assess their expression stability in rectal tumors as part of the screening phase." (PMID 33457124, 2020).
steatosis (1 paper, 2025). Increased lipid within the cytoplasm of cells. "We found that PUM1 expression was reduced in steatosis hepatocytes (PA-treated HepG2 cells and PA-treated mouse primary hepatocytes), but not in PA-treated macrophages and HSCs." (PMID 40689527, 2025). "Liver histology showed that PUM1 knockdown aggravated steatosis, ballooning, inflammation, and fibrosis in the liver of mice." (PMID 40689527, 2025). "Knocking down PUM1 aggravated lipid deposition and lipotoxic death in steatosis hepatocytes." (PMID 40689527, 2025). "PUM1 knockdown aggravated steatosis, ballooning, inflammation, and fibrosis in the liver of mice." (PMID 40689527, 2025). "Western blot analysis demonstrated that knockdown of PUM1 resulted in increased expression of sterol regulatory-element binding protein 1 (SREBP1), acetyl-CoA carboxylase 1 (ACC1), and fatty acid synthase (FASN) in steatosis hepatocytes." (PMID 40689527, 2025).
testicular cancer (1 paper, 2022). A primary or metastatic malignant neoplasm that affects the testis. "Taken together, we demonstrate the interplay between NANOS3, PUM1, and FOXM1 in regulating G2/M phase genes and disruption of this interplay in testicular cancer." (PMID 35743036, 2022). "This analysis showed a much wider expression pattern for PUM1, NANOS3, FOXM1, and target cell cycle genes in testis cancer compared to healthy testis samples including altered NANOS3-FOXM1 and PUM1-FOXM1 correlations." (PMID 35743036, 2022).
cancer (32 papers, 2008 to 2025). A tumor composed of atypical neoplastic, often pleomorphic cells that invade other tissues. "Because long G1 (i.e., slow cycling) and quiescence are hallmarks of cancer stem cells (CSCs), we wondered if Pum1-deficiency affected CSC-related properties of HCT116 and RKO cells." (PMID 35338151, 2022). "Nonetheless, the prognostic significance of PUM1 found in this study is consistent with findings in other cancers." (PMID 41155797, 2025). "Abnormal PUM expression patterns have been observed in various cancers, some of which vary between PUM1 and PUM2." (PMID 41155797, 2025). "Recently, research showed that the flavonoid morin has an affinity for PUM1 and substantially suppresses its expression, reducing the number of cancer stem cells." (PMID 38328550, 2024). "Increased expression of PUM1 has been directly correlated with cancer progression, while its silencing has demonstrated reduced cell proliferation, migration, and invasion ability." (PMID 37624174, 2023). "PUM1 regulates the expression of hematopoietic stem cells and promotes the migration of cancer cells." (PMID 33985534, 2021). "Pumilio RNA-binding family member 1 (PUM1) is described as an oncogene that plays an important role in a variety of malignant tumors, but its function in cetuximab resistance in CRC is unclear." (PMID 34447749, 2021). "Abnormal profiles of PUM expression have been shown in several types of cancer, in some of them being different for PUM1 and PUM2." (PMID 33401540, 2021). "In the TCam-2 seminoma cell line, it has recently been demonstrated that PUM1 and PUM2 regulate several mRNAs functionally linked to cancer." (PMID 33401540, 2021). "Human Pumilios, Pumilio1 (PUM1) and Pumilio2 (PUM2), are sequence-specific RBPs whose targets often encode proteins acting in cancer-related pathways." (PMID 31655860, 2020). "All but two of these RBPs (FXR1 and PUM1) are splicing factor genes and U2AF1 exhibited significant driver mutation patterns across a wide variety of cancer types." (PMID 32532357, 2020). "In the COSMIC database, 78, 114, 113, and 83 studies confirmed the correlation between HNRNPA2B1, BPTF, LRRK1, and PUM1 with cancer, respectively." (PMID 32300588, 2020). "Testicular cancers are the most frequently diagnosed malignant tumors in young Caucasian males, and their incidence has increased, highlighting the importance of the human male germ cell context in studying PUM1- and PUM2-controlled regulation." (PMID 32316190, 2020). "The cross-tissue analysis of 12 cancer types revealed that the most stably expressed genes were: PUM1 (SExp = 70), IPO8 (SExp = 61), UBC (SExp = 60), ACTB (SExp = 55), and RPN1 (SExp = 54)." (PMID 30881377, 2019). "SPIN1 (also known as SPINDLIN1) was selected as a candidate mRNA target for PUM1 via a RIP-Chip screening of human HeLa cancer cells, as it binds PUM1 and contains several PBE-like motifs in its 3′UTR." (PMID 30197756, 2018). "To identify mRNAs associated with human PUM proteins, we used a modified Ribonucleoprotein-ImmunoPrecipitation Microarray (RIP-Chip) approach on HeLa S3 cancer cells that express both PUM1 and PUM2." (PMID 18776931, 2008). "Recent studies have highlighted the potential of PUM1 as a therapeutic target for cancer treatment." (PMID 37624174, 2023). "Furthermore, the human Pum1 and Pum2 genes have been shown to be mis-expressed in various types of cancers, and there is increasing evidence that this misexpression impacts tumorigenesis." (PMID 37747106, 2023). "Additionally, the treatment group showed a significant decrease in PUM1 and cancer stem cell markers expression compared to the control group." (PMID 37624174, 2023). "In contrast, IPO8, PUM1 and—in case of cancer cell lines—HNRNPL showed the lowest variation." (PMID 34593877, 2021). "Thus, our results reinforce a new application of this gene as a marker for cancer and suggest that future studies aim at the function of PUM1 as cfDNA in cancer." (PMID 33522650, 2021).